GRIN2A (glutamate ionotropic receptor NMDA type subunit 2A)
Diseases named in the same sentence as GRIN2A in open-access papers (continued):
Sharing a sentence is not in itself a finding about the gene and the disease.
schizophrenia (continued). "Recent large-scale exome-sequencing efforts have uncovered rare genetic variants that confer a high risk for schizophrenia, including GRIN2A and AKAP11." (PMID 36914641, 2023). "These shared EEG abnormalities suggest that Grin2a and Akap11 deficiencies impact, at least in part, the same brain networks and circuits that go awry in schizophrenia patients." (PMID 36914641, 2023). "Differences in NMDA receptor activity through schizophrenia-associated genetic effects on GRIN2A is therefore likely to alter the maturation of relevant glutamatergic synapses and have a direct impact on synaptic plasticity throughout postnatal life." (PMID 34974922, 2022). "In cortical and hippocampal Camk2a neurons, we identified signature proteins linked to epilepsy (e.g., Dlg4) and schizophrenia (e.g., Grin2a)." (PMID 35614064, 2022). "The glutamate receptor subunit GRIN2A was recently found to be associated with schizophrenia in the largest GWAS of schizophrenia so far." (PMID 36618913, 2022). "Previously, common polymorphic variants from the promoter regions of GRIA1, GRIA3, GRIN1, or GRIN2A were associated with susceptibility to addiction, migraine, or schizophrenia." (PMID 34945722, 2021). "Recently, WES of 24,248 cases and 97,322 controls revealed ultra-rare coding variants in 10 genes and GRIN2A is appeared to confer risk as one of the strongly associated schizophrenia genes." (PMID 34946848, 2021). "Mutations in GRIN2A are previously associated with a range of neuropsychiatric phenotypes including mental retardation, epilepsy, schizophrenia, and BIP." (PMID 30930738, 2019). "In this study, we demonstrated that prenatal exposure to BP-3 caused substantial increase in Mef2c, Grin2a, and Chrna4 which corresponds to upregulation of these genes in brains of schizophrenia patients as detected in post-mortem." (PMID 30402708, 2019). "Genome wide significant associations with schizophrenia have been reported for at least two of the NMDAR genes- GRIN2A and GRIN2B." (PMID 29520222, 2018). "GRIN2A was recently shown to be associated with schizophrenia in the largest GWAS to date (Schizophrenia Working Group of the Psychiatric Genomics Consortium, 2014)." (PMID 29520222, 2018). "Consistent with a fundamental role for GluN2A-containing receptors in development and synaptic plasticity, recent genetic analyses implicate variation in the GRIN2A gene as major risk factors for schizophrenia and autism." (PMID 26829109, 2016). "The (GT)n polymorphism in the promoter of GRIN2A has been reported to be associated with schizophrenia and bipolar disorder." (PMID 23940648, 2013). "Common non-coding variants in GRIN2A have been associated with Huntington disease (HD) and schizophrenia, and rare mutations have been described in patients with neurodevelopmental phenotypes." (PMID 21876681, 2011). "The reduced GRIN2A/GRIN2B ratio in these studies may therefore be more likely to be associated with schizophrenia or psychosis." (PMID 41465140, 2025). "These dysfunctions are clinically associated with cognitive impairment in schizophrenia patients, with postmortem studies demonstrating low expression of GRIN2A in the dorsolateral prefrontal cortex and AMPA receptor trafficking in both schizophrenic patients and controls." (PMID 41523331, 2025). "GRIN2A variants have been found in patients with various neuropsychiatric disorders, including autism spectrum disorders, epilepsy, intellectual disability, attention-deficit/hyperactivity disorder, and schizophrenia." (PMID 41220606, 2025). "We hypothesise that the heterozygous loss of GRIN2A induces NMDAR hypofunction sufficient to confer a substantial risk of schizophrenia." (PMID 39501956, 2025).
schizophrenia (continued). "Fourth, activation of GRIN2A was prioritized as a mechanism to develop new antipsychotics around, and a clinical case report of schizophrenia in a carrier of a rare LoF variant in GRIN2A provided clues regarding the schizophrenia clinical presentation to target with this pharmacological strategy." (PMID 40701976, 2025). "Furthermore, the review explores genetic alterations in the glutamatergic system, focusing on modifications linked to GRIN2A and its associated miRNAs, which have been reported to have a notable impact on the occurrence of Schizophrenia." (PMID 38343691, 2024). "Likewise, given the key influence of NMDA receptor hypofunction in the pathophysiology of schizophrenia, the association GRIN2A and GRIN2B with presynaptic mGlu2 and mGlu3 in the context of schizophrenia certainly warrants further exploration." (PMID 38277461, 2024). "Several of the schizophrenia-associated variants in GRIN2A are located in the CTD." (PMID 37736757, 2023). "Importantly, language dysfunction is considered a disease defining symptom both of schizophrenia and disorders related to exonic variants of GRIN2A (epilepsy-aphasia spectrum disorders)." (PMID 36797233, 2023). "The mutations of GRIN2A in human could induce nervous system diseases such as single-gene epilepsies and schizophrenia." (PMID 37404751, 2023). "But the hypogyric subgroup exhibited a higher than expected presence of the schizophrenia-risk SNVs of GRIN2A (rs9940680 and rs1420040) and lower rate of the protective variant of GRM3 (s14513928; a lower rate of this protective variant is also notable in healthy siblings)." (PMID 37158213, 2023). "There are several interesting features of the GRIN2A rare variants reported in schizophrenia." (PMID 37736757, 2023). "These mouse EEG phenotypes reveal systems-level abnormalities caused by (even heterozygous) mutations in Grin2a and Akap11, and provide further justification, beyond their genetic validity, that these mouse mutants can serve as useful animal models of schizophrenia/bipolar disorder." (PMID 36914641, 2023). "Firstly, what do the schizophrenia-associated GRIN2A mutations and SNPs do to NR2A function?" (PMID 37736757, 2023). "Importantly, even in the heterozygous state (which is the most relevant to human schizophrenia), Grin2a mutations had a significant effect on resting (particularly during NREM sleep) and stimulus-evoked gamma power." (PMID 36914641, 2023). "In a separate study on another Pakistani family, heterozygous missense variants NRG3 p.(Glu651Lys) and GRIN2A p.(Arg1169Trp) were co-inherited in patients with schizophrenia from unaffected consanguineous parents who were carriers for only one of either variant." (PMID 36384485, 2022). "Convergent genetic evidence for GRIN2A as a schizophrenia susceptibility gene provides strong support for long-held (hypo-) glutamatergic theories of the disorder that were based on the observed induction of positive, negative, and cognitive symptoms in healthy adults after NMDA receptor antagonism." (PMID 34974922, 2022). "Thus, previous study has shown a correlation between the duration of the GRIN2A variable polymorphism (GT)n repeat and the severity of the chronic outcome of schizophrenia." (PMID 34685369, 2021). "This may indicate that dysfunction of NMDA receptor subunits can serve as a trigger for the development of schizophrenia, and significant mutations in the GRIN2A and GRIN2B genes can affect early or late onset." (PMID 34685369, 2021). "A previous study identified a variable (GT)n polymorphism in the promoter region of the GluN2A subunit gene (GRIN2A), and showed its association with schizophrenia in a case–control study, together with a correlation between the length of the repeat and the severity of chronic outcome." (PMID 34685369, 2021). "GRIN2A mutations have been found in patients with epilepsy-aphasia spectrum disorders, early-onset epileptic encephalopathy and schizophrenia." (PMID 29365063, 2018).
schizophrenia (continued). "Two de novo mutations in GRIN2A were found in sporadic schizophrenia patients." (PMID 30459650, 2018). "Schizophrenia is associated with a (GT)n repeat in the GRIN2A promoter that may increase disease risk by suppressing gene expression." (PMID 21876681, 2011). "Moreover, the schizophrenia-related GRIN2A variant exhibited a similar pattern suggesting that this typical imaging phenotype of schizophrenia may indeed be aggravated by a genetically driven dysfunction of NMDAR receptors." (PMID 36797233, 2023). "The functional correlates of the missense variants found in schizophrenia are unknown, but other GRIN2A point mutations can produce gain or loss of function, or other effects on receptor characteristics, depending in part on their domain location within the protein." (PMID 37736757, 2023). "Consequently, the observed connectivity changes may indicate that the common GRIN2A risk variant indeed promotes the excitatory/inhibitory imbalance in schizophrenia." (PMID 36797233, 2023). "This relationship might also apply within schizophrenia, whereby cases associated with GRIN2A point mutations have more prominent cognitive impairments (and other neurodevelopmental comorbidities) than cases attributed to GRIN2A protein-truncating variants." (PMID 37736757, 2023). "Mouse models with homozygous Grin2a-KO exhibit schizophrenia-related phenotypes, including hyperlocomotion, deficits in memory and impaired prepulse inhibition." (PMID 40931040, 2026). "These genes encompass high-odds risk genes of schizophrenia identified by SCHEMA, including Gria3, Grin2A, Herc1, and Trio." (PMID 39774335, 2025). "Grin2a encodes a subunit of the N-methyl-D-aspartate (NMDA) receptor, a postsynaptic glutamate receptor that is implicated in schizophrenia by psychopharmacology, and is also a common-variant risk gene by GWAS fine-mapping." (PMID 41022686, 2025). "Previous studies have shown that dysfunction of GRIN2A is probably important in the development of schizophrenia." (PMID 40259965, 2025). "Among these, the GRIN2A gene, encoding the GluN2A subunit of the NMDAR, has emerged as a significant contributor to disorders such as schizophrenia and the epilepsy spectrum." (PMID 40529501, 2025). "One of many examples of this age-dependence is illustrated by the Grin2a+/− mutant, which shows opposite direction of enrichment of human schizophrenia DEGs at 1 month versus 3 months of age." (PMID 41022686, 2025). "By these transcriptomic comparisons, the Grin2a+/− mouse at 3 months is the SCHEMA mutant most similar to human schizophrenia, in PFC and striatum." (PMID 41022686, 2025). "They reported that TC rs11644461 GRIN2A genotype carriers have higher severity of schizophrenia symptoms than CC genotype carriers." (PMID 40259965, 2025). "The core genes were identified in Cytoscape software and the results showed that NRXN, CACNA1C and GRIN2A are hub genes in schizophrenia." (PMID 40259965, 2025). "Human genetic studies have revealed rare missense and protein-truncating variants in GRIN2A, encoding for the GluN2A subunit of the NMDA receptors, that confer significant risk for schizophrenia (SCZ)." (PMID 38307912, 2024). "In schizophrenia, both human pharmacology and human genetics (see GRIN2A section below) implicate NMDAR receptor hypofunction." (PMID 37369776, 2024). "In iPSC-derived neurons from patients with schizophrenia, researchers have identified changes in the expression of various glutamate receptor subunits, including GRIN2A, GRIN2B, GRIK1, GRIK2, and GRM1, GRM7, as well as glutamate transporter genes." (PMID 39596430, 2024). "Among these genes, GRIN2A and SLC12A5, implicated in schizophrenia and bipolar disorder, were significantly upregulated in TL PVALB neurons and in psychiatric disease patients’ brain." (PMID 38864245, 2024). "GRIN2A rs11644461*T and GRIN2B rs7313149*T alleles have protective effect against developing the continuous type of schizophrenia." (PMID 36980845, 2023).
schizophrenia (continued). "The GRIN2A and GRIN2B genes are being extensively studied as plausible candidate genes for the susceptibility to schizophrenia and other neurodegenerative or neurodevelopmental disorders." (PMID 36980845, 2023). "One of ten genes reaching exome-wide significance, GRIN2A (glutamate ionotropic receptor NMDA type subunit 2A) is a particularly compelling SCHEMA gene for further study because it is also a significant GWAS hit for schizophrenia." (PMID 36914641, 2023). "We examined the association of 39 single nucleotide polymorphisms in eight genes (GRIN2A, GRIN2B, SLC1A2, SLC1A3, SLC17A7, GRM3, GRM7, and GRM8) involved in the glutamatergic system with the development of clinical heterogeneity of schizophrenia." (PMID 36980845, 2023). "Back-to-back papers in Nature last year provide a step-change in the evidence for involvement of the NMDA receptor in schizophrenia and, in particular, for a genetic contribution from GRIN2A." (PMID 37736757, 2023). "We previously showed that the GRIN2A and GRIN2B genes are associated with early onset of schizophrenia." (PMID 36980845, 2023). "These neurophysiologic findings further substantiate Grin2a and Akap11 mutants as genetic models of schizophrenia and identify potential biomarkers for stratification of schizophrenia patients." (PMID 36914641, 2023). "Nine genes are robustly associated with schizophrenia through deleterious mutations in these genes: SETD1A, CUL1, XPO7, TRIOCANCA1G, SP4, GRIA3, GRIN2A, and HERC1." (PMID 38911007, 2022). "Although, these GRIN2A and GRIN2B genes are also susceptible to early onset of schizophrenia function as well as to attentional impairment in ADHD (attention-deficit/hyperactivity disorder) and HD." (PMID 35958988, 2022). "Recent human genetic studies validated the central role of NMDAR in the development of schizophrenia where truncation of GRIN2A gene (NMDAR2A subunit) carries an odds ratio of 18.1 (3.74–172) for schizophrenia." (PMID 34307898, 2021). "At the same time, we were the first to obtain data on the association of the GRIN2A (rs7206256, rs11644461) and GRIN2B (rs7313149) genes with early onset of schizophrenia in the Russian population of the Siberian region." (PMID 34685369, 2021). "Earlier, we studied the role of GRIN2A and GRIN2B variants in antipsychotic-induced tardive dyskinesia in schizophrenia in terms of genetically determined increase in vulnerability to NMDA-induced excitotoxicity." (PMID 34685369, 2021). "In our study, we identified an association of GRIN2A rs7206256*A, GRIN2A rs1164446*GG/G, and GRIN2B rs7313149*A with the early onset of schizophrenia." (PMID 34685369, 2021). "As just one example, one of our short list of “most likely druggable” genes, GRIN2A, was previously reported to link schizophrenia with performance on an antisaccade task." (PMID 34035472, 2021). "The GRIN2A and GRIN2B genes are being actively investigated as candidate genes for the predisposition of schizophrenia and other neurodevelopmental and/or neurodegenerative disorders." (PMID 34685369, 2021). "In this study, we examined the contribution of GRIN2A and GRIN2B (Glutamate Ionotropic Receptor NMDA Type Subunit 2A/2B) polymorphisms to the clinical features of schizophrenia, such as the leading symptoms, the type of course, and the age of onset." (PMID 34685369, 2021). "Single nucleotide or dinucleotide-repeated polymorphisms of the NMDAR subunit genes, such as NR1 (GRIN1), NR2A (GRIN2A), and NR2B (GRIN2B), increase susceptibility to schizophrenia." (PMID 31417356, 2019). "Large-scale genome-wide association studies (GWAS) have identified a set of common genetic variants in glutamatergic genes in patients with schizophrenia, including, for instance, GRM3, GRIN2A, GRIA1, SRR, CLCN3, among others." (PMID 31431615, 2019). "Genome-wide association studies have reported that the NMDAR subunits encoding genes, GRIN2A and GRIN2B, are schizophrenia-related genes." (PMID 30459650, 2018).
schizophrenia (continued). "In our dataset, we detected AMPA and NMDA receptor subunits associated with schizophrenia (i.e., GRIA1 and GRIN2A) and with a spectrum of DD/ID, ASD and seizures, often in co-morbidity (GRIA3, GRIN1, GRIN2A, and GRIN2B)." (PMID 28713243, 2017). "Many genes associated with glutamateric neurotransmission have been previously implicated in schizophrenia, including GRM3, GRIN2A, SRR and GRIA1." (PMID 29181591, 2017). "Mutations in GRIN2A can induce idiopathic focal epilepsy, while GRIN1 has been associated with schizophrenia susceptibility." (PMID 25339366, 2015). "Several studies have shown associations between SNPs of GRIN2A and/or GRIN2B and neurological or psychiatric diseases, such as Huntington’s disease, schizophrenia, bipolar disorder and Alzheimer’s disease." (PMID 23408766, 2013). "Mouse models with Grin2a heterozygous null mutants (Grin2a-KO constitutively) exhibit schizophrenia-like phenotypes, including reduced activity in the prefrontal cortex and hippocampus, a hyperdopaminergic state in the stratum, and increased resting gamma oscillation power." (PMID 40931040, 2026). "GRIN2A has also been identified as a converging site of common and rare genetic variation in neuropsychiatric disorders presenting in adolescence and adulthood, particularly schizophrenia." (PMID 40226380, 2025). "Moreover, two genes, GRIN2A and SP4, were prioritised as credible causal candidates in the most recent large schizophrenia GWAS4." (PMID 40753099, 2025). "Genetic variation in GRIN1 has not been associated with schizophrenia, but rare mutations in GRIN2A, which encodes another subunit of NMDA receptors, increase the risk of developing schizophrenia by almost 20-fold." (PMID 38490084, 2024). "Importantly, in some cases, converging evidence from both common and rare variant studies implicates the same synaptic genes, including GRIN2A in schizophrenia." (PMID 38256020, 2024). "Against this backdrop, the phenotype of Grin2a+/− heterozygotes has also been examined recently, and is arguably of more relevance to schizophrenia than are the Grin2a+/− knockouts, given the protein-truncating hemizygous GRIN2A mutations and thence the presumed haploinsufficiency." (PMID 37736757, 2023). "As a result of this analysis, associations of four polymorphisms, GRIN2A rs9788936 (p = 0.001), GRIN2A rs8057394 (p = 0.011), GRIN2B rs7313149 (p = 0.016), and SLC1A2 rs12361171 (p = 0.040) with the intensity of symptoms in schizophrenia were identified." (PMID 36980845, 2023). "Prior to these new genetic findings in schizophrenia, Grin2a mouse models had already been well characterised, both electrophysiologically and behaviourally, reflecting the broad neuroscientific interest in NMDA receptors and their roles in neural functioning and synaptic plasticity." (PMID 37736757, 2023). "Moreover, GRIN2A rs7192557 contributes to the development of antipsychotic induced limb-truncal tardive dyskinesia in patients with schizophrenia." (PMID 36980845, 2023). "Meanwhile, mutant mice originally created not as a schizophrenia model but to elucidate gene function in the central nervous system, such as knockout mice for GRIN2A or GRIA3 encoding a glutamate receptor subunit, have not been subjected to omics analysis." (PMID 36878965, 2023). "Thirdly, GRIN2A is not the only glutamatergic gene which is now strongly implicated in schizophrenia by rare and/or common variants." (PMID 37736757, 2023). "Secondly, clarification is required as to the schizophrenia-related phenotypes to which GRIN2A genetic variation contributes, given the prior evidence that mutations in the gene primarily cause intellectual disability, epilepsy, and speech and language disorders." (PMID 37736757, 2023). "A further notable feature is that four of the schizophrenia-associated variants in GRIN2A occur in the CTD, whereas none occurred in this region in the 284 GRIN2A-associated neurodevelopmental disorder cases reported by Strehlow and colleagues." (PMID 37736757, 2023).